PICALM (phosphatidylinositol binding clathrin assembly protein)
Description:
Cytoplasmic adapter protein that plays a critical role in clathrin-mediated endocytosis which is important in processes such as internalization of cell receptors, synaptic transmission or removal of apoptotic cells. Recruits AP-2 and attaches clathrin triskelions to the cytoplasmic side of plasma membrane leading to clathrin-coated vesicles (CCVs) assembly. Furthermore, regulates clathrin-coated vesicle size and maturation by directly sensing and driving membrane curvature. In addition to binding to clathrin, mediates the endocytosis of small R-SNARES (Soluble NSF Attachment Protein REceptors) between plasma membranes and endosomes including VAMP2, VAMP3, VAMP4, VAMP7 or VAMP8. In turn, PICALM-dependent SNARE endocytosis is required for the formation and maturation of autophagic precursors. Modulates thereby autophagy and the turnover of autophagy substrates such as MAPT/TAU or amyloid precursor protein cleaved C-terminal fragment (APP-CTF).
Synonyms: CALM; CLTH; LAP
Tractability: Antibody: UniProt places it where antibodies can reach, with high confidence; its Gene Ontology location is reachable by antibodies, with high confidence. PROTAC: UniProt records ubiquitination sites on it; ubiquitination databases record sites on it; its protein half-life has been measured.
Gene: Protein-coding gene on chromosome 11 (85,957,171 to 86,069,882, reverse strand). Ensembl gene ENSG00000073921.
Subcellular location: Cell membrane; Membrane, clathrin-coated pit; Golgi apparatus; Cytoplasmic vesicle, clathrin- coated vesicle; Nucleus
Subcellular location (Human Protein Atlas): Vesicles
Pathways (Reactome):
Vesicle-mediated transport: Cargo recognition for clathrin-mediated endocytosis; Clathrin-mediated endocytosis; Golgi Associated Vesicle Biogenesis
Signal Transduction: RND3 GTPase cycle
Gene Ontology:
Molecular function: cadherin binding; clathrin binding; clathrin heavy chain binding; low-density lipoprotein particle receptor binding; protein binding; small GTPase binding; SNARE binding; tau protein binding; 1-phosphatidylinositol binding; amyloid-beta binding; phosphatidylinositol-4,5-bisphosphate binding; phospholipid binding
Biological process: amyloid-beta clearance by transcytosis; clathrin coat assembly; clathrin-dependent endocytosis; endocytosis; endosomal transport; intracellular iron ion homeostasis; membrane bending; multicellular organismal-level iron ion homeostasis; negative regulation of gene expression; negative regulation of protein localization to cell surface; negative regulation of protein localization to plasma membrane; negative regulation of receptor-mediated endocytosis; positive regulation of amyloid-beta formation; positive regulation of DNA-templated transcription; positive regulation of Ras protein signal transduction; receptor internalization; receptor-mediated endocytosis; regulation of amyloid precursor protein catabolic process; regulation of endocytosis; regulation of protein localization; regulation of vesicle size; vesicle budding from membrane; vesicle cargo loading; learning or memory; positive regulation of amyloid precursor protein catabolic process; and 5 more
Cellular component: cell surface; clathrin coat of coated pit; clathrin-coated pit; clathrin-coated vesicle; early endosome; endosome to plasma membrane transport vesicle; Golgi apparatus; membrane; neurofibrillary tangle; neuronal cell body; nucleus; plasma membrane; clathrin-coated endocytic vesicle; cytosol; extrinsic component of presynaptic endocytic zone membrane; perinuclear region of cytoplasm; postsynaptic membrane; presynaptic membrane; synaptic vesicle; vesicle; endomembrane system
Genetic constraint (gnomAD): Loss-of-function variants: 6 observed, 18.31 expected, observed/expected ratio (o/e) 0.33, 90% interval 0.18 to 0.65. The upper end of that interval is the gene's LOEUF score, 0.65, which puts it in group 2 of 6, group 1 being the genes least tolerant of losing a copy. Missense variants: 178 observed, 221.8 expected, observed/expected ratio (o/e) 0.8, 90% interval 0.71 to 0.91. Synonymous variants: 103 observed, 84.1 expected, observed/expected ratio (o/e) 1.22, 90% interval 1.04 to 1.44.
Cancer hallmarks: change of cellular energetics (promotes)
Homologues: Orthologues: chimpanzee PICALM (99% identical), macaque PICALM (99% identical), dog PICALM (99% identical), rabbit PICALM (99% identical), guinea pig PICALM (99% identical), pig PICALM (98% identical), mouse Picalm (98% identical), rat Picalm (97% identical), tropical clawed frog picalm (84% identical), zebrafish picalma (77% identical), zebrafish picalmb (74% identical), Drosophila melanogaster lap (46% identical), and 1 more. Paralogues in human: SNAP91 (56% identical).
Diseases named in the same sentence as PICALM in open-access papers:
PICALM is named in the same sentence as 66 diseases in open-access papers, as found by Europe PMC text mining. Sharing a sentence is not in itself a finding about the gene and the disease. The quoted sentences say what the papers report.
Alzheimer disease (72 papers, 2010 to 2025). A progressive, neurodegenerative disease characterized by loss of function and death of nerve cells in several areas of the brain leading to loss of cognitive function such as memory and language. "PICALM is a genetic risk factor for late-onset Alzheimer’s disease that participates in amyloid-β transcytosis and processing of amyloid precursor protein (APP)." (PMID 38594674, 2024). "PSD95 is an important postsynaptic scaffolding protein and decreased levels are associated with Alzheimer’s disease pathology; PICALM is involved with endocytosis and Alzheimer’s disease risk; while p62 plays a key role in autophagy." (PMID 35248135, 2022). "PICALM rs3851179, one of the genes most frequently linked to susceptibility of late-onset Alzheimer’s disease (LOAD), plays a crucial role in regulating amyloid precursor protein, and amyloid β (Aβ) transcytosis." (PMID 36552141, 2022). "Examples are PICALM/CALM contributing to Alzheimer’s disease pathology, C9ORF72 implicated in ALS and FTD and several genes linked to Parkinson’s disease such as LRRK2, VPS35, SNCA, Synj1 and EndoA." (PMID 34988081, 2021). "Genome wide association studies (GWAS) have identified and validated the association of the PICALM genotype with Alzheimer’s disease (AD)." (PMID 32372909, 2020). "PICALM has consistently been associated with Alzheimer’s disease in several GWA studies with risk estimates in the range of 1.14–1.27." (PMID 30830563, 2019). "Unc-11 is orthologous to PICALM, another well-established late onset Alzheimer’s disease (LOAD) risk gene known to play a role in clathrin-mediated endocytosis." (PMID 30497524, 2018). "The repair response is also blocked by loss of calpain function, and is altered by loss-of-function mutations in the C. elegans orthologs of BIN1 and PICALM, well-established risk genes for late onset Alzheimer’s disease." (PMID 30497524, 2018). "The PICALM gene encodes a phosphatidylinositol-binding clathrin assembly protein, and polymorphisms in this gene are associated with the risk of Alzheimer’s disease in humans." (PMID 28923017, 2017). "Phosphatidylinositolbinding clathrin assembly protein (PICALM) gene is one novel genetic player associated with late-onset Alzheimer’s disease (LOAD), based on recent genome wide association studies (GWAS)." (PMID 27117083, 2016). "In 2009 Genome Wide Association Studies (GWAS) were published describing polymorphisms in a number of genes associated with an increased risk of developing Alzheimer’s disease (AD) including PICALM (phosphatidylinositol binding clathrin assembly protein)." (PMID 27430330, 2016). "Chromosomal translocations that result in the fusion of PICALM to heterologous proteins cause leukemias, and genome-wide association studies have linked PICALM Single Nucleotide Polymorphisms (SNPs) to Alzheimer’s disease." (PMID 26075887, 2015). "Multiple independent Genome Wide Association Studies (GWAS) indicate that PICALM SNPs play a role in the development of late-onset Alzheimer’s Disease (AD)." (PMID 26075887, 2015). "A nominally significant association was observed with the PICALM rs561655 variant, but the direction of effect was opposite to that expected from earlier studies of Alzheimer’s disease." (PMID 24438528, 2014). "The gene for CALM (PICALM) was identified as a risk gene in late onset Alzheimer’s disease and is known to participate in gene fusions that cause leukemia." (PMID 25329427, 2014). "PICALM has also recently been implicated in late-onset Alzheimer's disease by genome-wide association studies." (PMID 22952941, 2012). "Alterations of the human PICALM gene are present in aggressive hematopoietic malignancies, and genome-wide association studies have recently linked the PICALM locus to late-onset Alzheimer's disease." (PMID 22952941, 2012).
Alzheimer disease (continued). "The CALM/PICALM gene has also been directly implicated in alterations in cognitive function with increasing age in risk of developing Alzheimer's disease and in modifying the toxicity of Aβ in a yeast, C. elegans and primary rat cortical neuron models." (PMID 22118466, 2011). "PICALM is one of the most significant susceptibility factors for Alzheimer’s disease (AD)." (PMID 36707892, 2023). "However, we found that Alzheimer’s disease risk factor PICALM, is O-GlcNAcylated and its O-GlcNAcylation is upregulated by thiamet G." (PMID 35248135, 2022). "It is still unclear how PICALM mutations influence the risk of Alzheimer’s disease (AD)." (PMID 33170153, 2020). "hsa_circ_0023919 is located in PICALM gene that is involved in clathrin-mediated endocytosis at neuromuscular junctions and single nucleotide polymorphism upstream of the gene has been associated with Alzheimer’s disease." (PMID 31175544, 2019). "The PICALM rs541458 T allele has been recognized as a risk factor for late-onset Alzheimer’s disease, and age might modulate the effects that genetic factors have on cognitive functions and brain." (PMID 28116548, 2018). "We tested for association with loci previously associated with Alzheimer’s disease risk and, despite the small size of the study, we detected associations with age at onset of Alzheimer’s disease in Down syndrome with PICALM (β = 3.31, p = 0.011) and the APOE loci (β = 3.58, p = 0.014)." (PMID 23601808, 2013). "CALM's role in directing the endocytosis of small R-SNAREs may provide insight into the association of CALM/PICALM mutations with growth retardation, cognitive defects, and Alzheimer's disease." (PMID 22118466, 2011). "One locus overlapped with a known Alzheimer's disease GWAS locus (EED/PICALM) and 2 with GWAS loci for circulating ω-3 fatty acids (SRSF4 and PSMG1)." (PMID 40949174, 2025). "In conclusion, we found that three genes (APOE, PICALM, and TSPOAP1) associated with Alzheimer’s disease in EA are also associated with measure of cognitive functions in South Asians living in India, with the association primarily driven by missense/LoF SNVs." (PMID 39149469, 2024). "Potential insights on the molecular mechanisms of placental MDMX and PICALM were gained, respectively, from the cancer and Alzheimer’s disease literature." (PMID 38594674, 2024). "The PICALM pathway function in Alzheimer’s dementia confirms that clathrin-mediated endocytosis is a significant technique in amyloid-β salvage through the BBB." (PMID 37995081, 2024). "Further, decreasing the expression of PICALM has been shown to reduce endocytosis and the activity of the β-secretase enzyme, thought to play a major role in the pathogenesis of Alzheimer’s disease." (PMID 38036718, 2023). "PICALM is integral to endocytosis and has been correlated with levels of autophagy-related proteins in neuropsychiatric disease contexts, especially Alzheimer's disease." (PMID 38036718, 2023). "PICALM, the gene encoding phosphatidylinositol binding clathrin assembly protein PICALM, is a highly validated genetic risk factor for late onset Alzheimer’s disease (LOAD), and one of the most significant susceptibility factors for LOAD after APOE and BIN1." (PMID 36707892, 2023). "While differential modulation of APP processing and Aβ transcytosis by PICALM has been reported, significant effects of PICALM modulation of tau pathology progression have also been evidenced in Alzheimer’s disease models." (PMID 36552756, 2022). "Baseline participant characteristics as stratified by Apolipoprotein E (APOE) genotype (ε4-/ε4+) and Alzheimer’s disease genetic risk score (AD-GRS; Clusterin + Complement receptor 1+ Phosphatidylinositol-binding clathrin assembly protein)." (PMID 34603005, 2021).
Alzheimer disease (continued). "In fact, variants at numerous other genetic loci related to endocytic trafficking and synaptic maintenance have been discovered as risk factors for Alzheimer’s disease (BIN1, PICALM, CD2AP, SORL1) and Parkinson’s disease (SNCA, LRRK2, SH3GL2/EndoA, RAB7L1)." (PMID 32286230, 2020). "In this review we discuss our current knowledge of the risk genes APOE4, BIN1, CD2AP, PICALM, PLD3 and TREM2 and their impact on endolysosomal (dys)regulations in the light of late-onset Alzheimer’s disease pathology." (PMID 31159836, 2019). "Recently new light was shed on the function of PICALM in Alzheimer’s disease pathology, emphasizing clathrin-mediated endocytosis as a potential important mechanism in amyloid-β clearance across the blood–brain barrier." (PMID 30830563, 2019). "We genotyped four variants in PICALM, BIN1, CD2AP, and RIN3 previously identified as top hits for Alzheimer’s disease, in two prospective studies of the general population totaling 74,754 individuals." (PMID 30830563, 2019). "Genetic variants in PICALM, BIN1, CD2AP, and RIN3 are associated with increased risk of Alzheimer’s disease, all dementia, and suggested vascular dementia independent of the strong APOE ε4 allele." (PMID 30830563, 2019). "Other RBPMS partners we identified included PICALM, a clathrin adaptor with a role in Alzheimer's disease, TCF7L2, a Wnt signaling transcription factor and PATZ1, a transcriptional regulator with a role in cell death and proliferation and differentiation." (PMID 27107012, 2016). "We recently identified PICALM (CALM; phosphatidylinositol binding clathrin assembly protein), recently associated with Alzheimer’s disease, as an important regulator of both the homotypic fusion and the heterotypic fusion of autophagic precursors." (PMID 25461811, 2015). "While PTK2B, IL8 and HLA-DRB5 are clearly involved in Alzheimer pathology, there are controversial studies about the involvement of PICALM in Alzheimers disease." (PMID 25765079, 2015). "Recent genome-wide association studies of Alzheimer's disease (AD) have identified variants in BIN1, CLU, CR1 and PICALM that show replicable association with risk for disease." (PMID 21347408, 2011). "Recently, two large genome wide association studies in Alzheimer disease (AD) have identified variants in three different genes (CLU, PICALM and CR1) as being associated with the risk of developing AD." (PMID 20209083, 2010). "In conclusion, we found that three genes (APOE, PICALM, and TSPOAP1) associated with Alzheimer’s disease in EA are also associated with the measure of cognitive functions in South Asians living in India, with the association primarily driven by missense/LoF SNVs." (PMID 40565532, 2025). "Moreover, genetic loci relevant to Alzheimer’s disease, such as PICALM and APOE, appear to converge with PD pathophysiological networks." (PMID 40178685, 2025). "Study of miRNA involvement in Alzheimer’s disease pathogenesis is relevant, since the associations of protein-coding genes (APOE4, ABCA7, BIN1, CLU, CR1, PICALM, TREM2) with the disease revealed as a result of GWAS make it difficult to explain its complex pathogenesis." (PMID 38680184, 2024). "PICALM and CLU genes have been linked to alterations in brain biochemical processes that may have an impact on Alzheimer’s disease (AD) development and neurophysiological dynamics." (PMID 34650147, 2021). "A zebrafish model of Alzheimer’s disease (AD) is characterized by neuronal tau aggregates and was found to have reduced aggregate clearance and decreased Lc3-II levels upon overexpression of phosphatidylinositol binding clathrin assembly protein (Picalm)." (PMID 28698482, 2017). "It had been previously hypothesized that faulty endocytosis plays a role in the neuronal degeneration associated with Alzheimer's disease, and this notion is supported by the detection of specific PICALM SNPs in Alzheimer’s Disease patients." (PMID 22952941, 2012).
Alzheimer disease (continued). "Proteins expressed by HSV-1 are homologous to all of the protein products of the major susceptibility gene in Alzheimer's disease (APOE, clusterin, complement receptor 1, and PICALM) as well as to APP and tau and over 100 others implicated in genetic association studies." (PMID 21234306, 2010). "In Alzheimer’s disease (AD), we analyzed RNA-seq data from the AD Functional Genomics consortium FunGen-xQTL project and identified unproductive splicing events in 18 AD risk genes, including TSPAN14, PICALM, and CASS4, likely mediating genetic effects on disease risk." (PMID 40291686, 2025). "Interestingly, several transcriptome-wide significant and colocalized genes outside genome-wide significant GWAS loci point to biologically relevant pathways related to neurodevelopment and neurodegeneration (PICALM, a known Alzheimer disease gene, CAMSAP2, AGTPBP1, SETD1A, EPRS, PADI2 and PSAP)." (PMID 38811690, 2024). "Genetic studies including genome-wide studies have also associated inflammation-related genes to the etiology of Alzheimer’s disease (i.e. ABCA7, CLU, CR1, HLA-DRB1, HLA-DRB5, PICALM, and TREM2), further supporting the concept of neuroinflammation as a pathogenic factor in Alzheimer’s disease." (PMID 34335238, 2021). "Finally, the role of PICALM in iron homeostasis may also be relevant to the pathogenesis of Alzheimer's Disease (AD)." (PMID 22952941, 2012). "This method will enable researchers to carry out genetic polymorphism studies for genetic risk factors associated with late-onset Alzheimer’s disease (BIN1, CLU, ABCA7, CR1 and PICALM) without the use of expensive instrumentation and reagents." (PMID 23419238, 2013).
dementia (16 papers, 2014 to 2026). Loss of intellectual abilities interfering with an individual's social and occupational functions. "Given its direct involvement in β-amyloid transport, it is reasonable that PICALM is associated with HMSE score, a dementia screener, which likely identifies cases of AD and other dementia that have progressed." (PMID 40565532, 2025). "Subjects with VaD/mixed dementia had 98% higher PICALM mRNA levels, but 75% lower ABCA7 mRNA expression than healthy individuals." (PMID 36982820, 2023). "Previous studies have shown that the effect of the APOE gene on the risk of cognitive decline and dementia was modified by other genetic factors, including ABCA7, SORL1, PICALM, CR1, BIN1, and TREM2, showing complex gene-gene interactions." (PMID 34214049, 2021). "The association between the PICALM A allele and better composite cognitive scores was found in older men without dementia." (PMID 32372909, 2020). "Our previous report suggested PICALM and APOE as risk factors for early onset of dementia in DS." (PMID 24462566, 2014). "In summary, our findings reinforce previous research and suggest that APOE and PICALM shape the functional architecture of the resting brain even in the absence of dementia." (PMID 40095677, 2025). "We have previously shown that in DS polymorphisms in PICALM and APOE are associated with AOO of dementia, and there is a nonsignificant trend in risk allele loading derived from AD meta-analysis." (PMID 24462566, 2014).